ATF3 (activating transcription factor 3)
Diseases named in the same sentence as ATF3 in open-access papers (continued):
Sharing a sentence is not in itself a finding about the gene and the disease.
cardiac hypertrophy (continued). "In vivo, the cardiac expression of ATF3 is induced by ischemia/reperfusion and Ang II, and transgenic mice with cardiac-specific expression of ATF3 exhibit atrial enlargement, atrial and ventricular hypertrophy, fibrosis, reduced contractility and aberrant conduction." (PMID 22053207, 2011). "QL may alleviate cardiac hypertrophy and cardiac dysfunction via the miR-382-5p/ATF3 axis." (PMID 39332150, 2024). "Finally, mice deficient in Atf3 which encodes transcription factor 3 (ATF3), a partner protein of FOS, exhibited fibrosis and cardiac hypertrophy in response to pressure overload, suggesting an important transcriptional role for Atf3 in the cardiovascular system." (PMID 36736425, 2023). "Furthermore, Atf3, which is induced by ROS and pathogens including T. cruzi, may promote fibrosis and cardiac hypertrophy." (PMID 38062533, 2023). "Moreover, the rate of protein synthesis, another important hallmark of pathological cardiac hypertrophy, was not increased but even slightly decreased in response to ATF3 overexpression." (PMID 25136830, 2014). "Therefore, ATF3 may serve as an important drug target toreduce the detrimental consequences of heart hypertrophy." (PMID 23874609, 2013). "However, the effect of ATF3 deficiency on cardiac hypertrophy, especially, when induced by pathological stimuli, has not been determined." (PMID 22053207, 2011). "Therefore, it is likely that ATF3 is necessary in the defense against pathological stress in the heart, and its up-regulation may be protective in the progression of cardiac hypertrophy." (PMID 22053207, 2011). "In conclusion, this study reveals a previously unknown effect of ATF3 on cardiac hypertrophy, dysfunction and fibrosis in response to hypertrophic stimuli by the negative feedback to the ERK and JNK pathways and regulation of pro-fibrotic cytokines and collagen content." (PMID 22053207, 2011). "It seems obscure that the role of ATF3 in cardiac hypertrophy is whether detrimental or protective." (PMID 22053207, 2011). "Activating transcription factor 3 (ATF3) in cardiac fibroblasts, via HDAC inhibition, suppresses the p38MAPK pathway, thereby limiting cardiac hypertrophy." (PMID 31434333, 2019). "Thus, csMed1-/- mice may have induced ATF3 levels as a protection against cardiac hypertrophy." (PMID 27548259, 2016). "Consistent with thereduced cardiac hypertrophy in the ATF3 KO mice, the induction of hypertrophymarkers βMHC and BNP in the ATF3 KO mice were significantly dampened in response toPE infusion, compared to the wild-type mice." (PMID 23874609, 2013). "Activating transcription factor 3 (ATF3) is a member of the ATF/CREB family of transcription factors involving in many important human diseases including cancer, atherosclerosis, infections, cardiac hypertrophy, and hypospadias." (PMID 27146783, 2016). "Here we show that the overexpression of ATF3 did not affect the gene expression of cardiac hypertrophy markers such as the natriuretic peptides ANP and BNP, α- and β-MHC, or cardiac and skeletal α-actin isoforms." (PMID 25136830, 2014). "The effects of ATF3 on cardiac hypertrophy, dysfunction and fibrosis are probably mediated by negative feedback to the ERK and JNK pathways and regulation of pro-fibrotic cytokines." (PMID 22053207, 2011). "We demonstrated that high ATF3 expression was not only in response to aortic banding in mice but also in the hearts of patients with DCM, which suggests that ATF3 is involved in the development of cardiac hypertrophy." (PMID 22053207, 2011). "However, the role of ATF3 in cardiac hypertrophy is controversial.The lack of ATF3 expression was shown to promote heart hypertrophy in response tothe aortic banding pressure overload model, suggesting a role for ATF3 to suppress hypertrophy." (PMID 23874609, 2013). "However, the effect of ATF3 on cardiac hypertrophy induced by a pathological stimulus has not been determined." (PMID 22053207, 2011).
Obesity (28 papers, 2010 to 2025). Accumulation of substantial excess body fat. "ATF3 deficiency worsened obesity-related DN, increasing glomerular fibrosis, mortality, and inflammation." (PMID 41369384, 2025). "Deficiency in ATF3 exacerbates obesity and metabolic dysregulation in mice subjected to a high-fat diet." (PMID 40244284, 2025). "Here, we demonstrated that Atf3 loss exacerbated HFD/STZ-induced obesity-related DN, reduced body weight, and increased mortality and glomerular fibrosis in vivo." (PMID 41369384, 2025). "The findings suggest ST32da is a promising therapeutic candidate for obesity-related DN and associated metabolic disturbances, acting through ATF3 induction to suppress renal inflammation, lipotoxicity, and fibrosis." (PMID 41369384, 2025). "In contrast, adeno-associated virus 8 (AAV8)-virus-mediated ATF3 restoration reversed the obesity exacerbation and metabolic disorders in HFD-fed ATF3−/− mice." (PMID 35326476, 2022). "By contrast, tissue-specific ATF3 deficiency exacerbates cardiomyopathy induced by obesity-related inflammation." (PMID 34172832, 2021). "Lipid-rich diet and obesity is known to cause lipid accumulation in hepatic cells, leading to induction of stress signals and activation of ATF3, an adaptive-response gene." (PMID 32075973, 2020). "Moreover, gene polymorphism studies have implicated ATF3 in human obesity, suggesting broader metabolic relevance." (PMID 41369384, 2025). "Moreover, ATF3 was identified as a key regulator of ’liver module 15’ —orchestrating an important supernetwork associated with obesity, diabetes, cholesterol metabolism, inflammation and atherosclerosis." (PMID 36144244, 2022). "Moreover, ATF3 has been shown to contribute to mitochondrial dysfunction associated with obesity in mice, and its overexpression in 3T3L-1 cells also decreased the expression of mitochondrial genes." (PMID 34968255, 2021). "Here, we demonstrated that loss of ATF3 in vivo aggravated HFD-induced obesity and metabolic dysfunction in mice, with increased TG level, insulin resistance, and hepatic steatosis, along with loss of normal thermoregulation under cold stress and decreased energy expenditure." (PMID 31667363, 2019). "In this study, we demonstrated the potency of ST32da, an ATF3 inducer derived from Salvia miltiorrhiza, as a novel class of drugs for obesity-related metabolic disorders, including obesity-related DN." (PMID 41369384, 2025). "We investigated the therapeutic potential of ST32da, a synthetic ATF3 inducer derived from Salvia miltiorrhiza, in mitigating obesity-related DN in both in vivo and in vitro models." (PMID 41369384, 2025). "In conclusion, this study identified ST32da as a novel anti-obesity drug that leverages the anti-inflammatory effect of ATF3 to protect against DN and kidney lipotoxicity." (PMID 41369384, 2025). "Our study indicated the effectiveness of SW20.1, an ATF3 expression inducer, in reducing and preventing obesity and its related metabolic disorder through the ATF3–resistin pathway." (PMID 37371606, 2023). "Consistent with its function in the inhibition of adipocyte differentiation, ATF3 exerts an anti-obesity effect in mice." (PMID 36472556, 2023). "Both ST32db and ST32C can upregulate ATF3; however, their anti-obesity effects are weaker than those of tanshinone I and II, whose effects can be sustained for approximately 5 to 6 weeks after treatment." (PMID 35326476, 2022). "Overall, ST32db, a single compound modified from S. miltiorrhiza extract, has anti-obesity effects through ATF3-mediated C/EBPα downregulation and the CHOP pathway." (PMID 35326476, 2022). "The results for SME and ST32db in this paper are a proof of concept showing that the prevention of obesity and related metabolic problems can be regulated through ATF3-related pathways." (PMID 35326476, 2022). "In the future, the transcriptional and epigenetic regulation of ATF3 in adipogenesis represents a new direction for obesity research." (PMID 35326476, 2022).
Obesity (continued). "ATF3 has also been suggested to be a marker of ER stress, and it negatively affects ER stress in obesity-related diabetes and in renal tissue failure due to obesity-lipotoxicity-induced ATF3 activation and ER stress." (PMID 34172832, 2021). "Our recent study showed that ATF3 KO mice exhibit metabolic dyshomeostasis, including obesity and insulin resistance, compared with WT mice after HFD feeding." (PMID 32922364, 2020). "Our findings confirm ATF3 inducers as promising drug candidates in treating and preventing obesity and metabolic dysfunction." (PMID 31667363, 2019). "Although the biological functions of ATF3 have been widely studied, the specific role of ATF3 in obesity regulation and energy metabolism remains to be fully explored." (PMID 31667363, 2019). "Our study identified the ATF3 inducer ST32da as a promising therapeutic drug for treating diet-induced obesity and related metabolic disorders." (PMID 31667363, 2019). "Here, genetic deletion of activating transcription factor 3 (ATF3−/−) in mice under a high-fat diet (HFD) resulted in obesity and insulin resistance, which was abrogated by virus-mediated ATF3 restoration." (PMID 31667363, 2019). "In the present study, deletion of ATF3 in mice aggravated high-fat diet (HFD)-induced obesity and metabolic dysfunction." (PMID 31667363, 2019). "We previously demonstrated that the ATF3 inducer ST32db may have beneficial effects in obesity and metabolic dyshomeostasis." (PMID 41465302, 2025). "Using various obesity-related DN mouse models, we showed that ST32da-induced ATF3 benefits obesity-related DN and improves high-glucose-induced inflammatory reactions in mesangial cells by inhibiting the proapoptotic molecule RARRES1, activated via the paracrine pathway." (PMID 41369384, 2025). "Notably, ST32db ameliorates HFD-induced obesity and metabolic dysfunction via ATF3-dependent suppression of C/EBPα-driven adipogenic programs." (PMID 41369384, 2025). "In anti-obesity studies, Atf3−/− mice exhibited severe liver lipid deposition compared to WT mice." (PMID 41369384, 2025). "In addition, ATF3 was demonstrated to inhibit the differentiation of 3T3-L1 adipocytes and has been studied in obesity-related cancers, such as the colorectal one." (PMID 37447165, 2023). "The results of this study indicate that SW20.1 may prevent obesity and its related metabolic syndrome by inducing ATF3 expression and inhibiting the crucial upstream resistin-related pathway." (PMID 37371606, 2023). "Atf3 overexpression can induce adipocyte browning and resistance to obesity in mice." (PMID 38097709, 2023). "In view of these studies, ATF3 may be a good therapeutic target for the modulation of adipocyte differentiation to combat obesity." (PMID 36472556, 2023). "ATF3 can also transcriptionally repress adiponectin receptor-2 (AdipoR2) gene expression by directly binding to the 5′ flanking promoter region of AdipoR2 and thus interfere with the protective effect of adiponectin on obesity-related insulin resistance." (PMID 36472556, 2023). "Furthermore, 16C (an ATF3 stimulant) effectively alleviated metabolic syndrome in mice with HFD-induced obesity." (PMID 37371606, 2023). "Moreover, it has been demonstrated that ATF3 genotypes/haplotypes cooperate with obesity to set the levels of C-reactive protein (CRP), which is an acute-phase protein correlated with poor prognosis in various types of cancer and obesity state." (PMID 37447165, 2023). "Moreover, the literature shows that sulfuretin, a major flavonoid from Toxicodendron vernicifluum, effectively prevents HFD-induced obesity via ATF3 induction." (PMID 35326476, 2022). "Based on our previous studies showing that ATF3 overexpression could suppress obesity, we focused on ATF3 in the present study." (PMID 35326476, 2022). "One of them, ST32da, an ATF3 inducer, has been shown to exert anti-obesity functions." (PMID 35326476, 2022).
Obesity (continued). "This evidence indicates that ATF3 may play a protective role in obesity and obesity-related metabolic diseases." (PMID 35326476, 2022). "Following the association between ATF3 and HDAC1, whether obesity is also reduced through the NF-κB pathway and adipogenesis/adipogenesis-targeted genes are regulated by NF-κB will be assessed in future work." (PMID 35326476, 2022). "HFD-fed ATF3−/− mice exhibited aggravated obesity and metabolic dysfunction." (PMID 34968255, 2021). "ATF3 may have beneficial properties in terms of inhibiting obesity-induced cytokines in vivo by targeting muscle, adipocytes, or other organs." (PMID 31667363, 2019). "ATF3 inducer could be a novel class of anti-obesity drug to treat diet-induced obesity and related metabolic disorders." (PMID 31667363, 2019). "The ATF3-inducer ST32da may have therapeutic benefits in individuals with obesity and metabolic dysfunction." (PMID 31667363, 2019). "In addition, physiological conditions like exercise induce GDF-15 could have a protective role against obesity and insulin resistance and also eliminate its reinforced stress markers like Atf3, Atf6, and Xbp1s in skeletal muscle after exercise." (PMID 38409184, 2024). "Therefore, it is important to further clarify the biological functions of ATF3 in different stages of adipocyte development in obesity, which will be more conducive to the development of intervention strategies for metabolic diseases based on targeting ATF3 in the future." (PMID 36472556, 2023). "Therefore, we hypothesized that ST32db might have an excellent anti-obesity effect via its strong ATF3 inducibility." (PMID 35326476, 2022). "Therefore, ST32db may exert its beneficial effects by activating ATF3, effectively ameliorating obesity and related metabolic disorders in HFD-induced obese mice." (PMID 35326476, 2022). "Previous studies have suggested that ATF3 could be a target for obesity treatment." (PMID 35326476, 2022). "Therefore, ST32da may exert its beneficial effects specifically via ATF3 activation and effectively protect against obesity in addition to lowering metabolic dysregulation in HFD-fed obese mice." (PMID 31667363, 2019). "Therefore, ATF3 may play a role in impaired adipocyte differentiation in obesity such that excess lipids cannot be stored adequately in the WAT, thus inducing obesity and its related metabolic disorders." (PMID 30246803, 2018). "ST32da was administered to db/db knockout and DBA mice to establish obesity-related DN models, and a high-fat diet (HFD)-induced mouse model of obesity-related DN was used to investigate the effects of Atf3 knockout." (PMID 41369384, 2025). "Very recently, two studies have shown that hepatic ATF3 expression is markedly reduced in patients with NAFLD and in mouse models of diabetes or obesity." (PMID 36472556, 2023). "Our data also showed that ATF3 can promote white-to-brown adipocyte transdifferentiation to increase energy expenditure and reduce WAT depots, thus mitigating obesity." (PMID 31667363, 2019). "Our results indicate that HPWE treatment attenuates the expression of PLIN1 and ATF-3, thereby supporting the hypothesis that HPWE exerts anti-obesity effects in vitro." (PMID 41155164, 2025). "Here, ATF3 deficiency produced no change in hepatic triglyceride levels in pre-hepatectomised HFD-fed mice, probably due to their milder phenotype of obesity and hyperglycaemia compared with ZDF rat." (PMID 36690638, 2023). "ST32db, a novel synthetic derivative similar in structure to compounds from S. miltiorrhiza extract, ameliorates obesity and obesity-induced metabolic syndrome in HFD-fed wild-type mice but not ATF3−/− mice." (PMID 35326476, 2022). "Coupled with the excellent anti-obesity effect of SME, we are interested in whether the major components in SME can also upregulate ATF3 expression." (PMID 35326476, 2022).
Obesity (continued). "Therefore, in this study, we investigated the antiobesity and anti-metabolic syndrome effects of SW20.1 and ST32db in mice with HFD-induced obesity and explored whether the molecular mechanism of SW20.1 involves the ATF3-medicated signaling pathway." (PMID 37371606, 2023). "In addition, an ATF3 inducer, ST32da, suppressed HFD-induced obesity in mice." (PMID 31667363, 2019). "However, given that ATF3 increases hepatic lipogenesis and lipid accumulation, ATF3 may exacerbate NASH through a synergistic effect on lipogenesis and hepatocellular death in the presence of severe obesity and hyperglycaemia." (PMID 36690638, 2023). "It is interesting to note activated CREB has been demonstrated in adipose cells under obese conditions, where it promotes insulin resistance by triggering expression of ATF3 and downregulating expression of GLUT4, indicating CREB plays and negative role in obesity induced insulin resistance." (PMID 32660483, 2020). "However, ATF3 regulation of the change in WAT and BAT in HFD-induced obesity and related metabolic disorders has not been investigated before." (PMID 31667363, 2019).